MUC1 (mucin 1, cell surface associated)
Diseases named in the same sentence as MUC1 in open-access papers (continued):
Sharing a sentence is not in itself a finding about the gene and the disease.
endometrial cancer (9 papers, 2006 to 2025). Primary or metastatic malignant neoplasm involving the endometrium (mucous membrane that lines the endometrial cavity). "In endometrial cancer, loss of polarity coupled with elevated expression of both MUC1 and EGFR could enhance the activity of this positive feedback loop." (PMID 27092881, 2016). "We observed indications that MUC1 driven EGFR regulation occurs in endometrial cancers and is likely manifest at two levels: 1) by elevating EGFR levels transcriptionally and; 2) by enhancing EGFR signaling." (PMID 27092881, 2016). "In accordance with previous reports, MUC1 increases cellular proliferation, survival and spheroid formation in endometrial cancer cells." (PMID 27092881, 2016). "Altogether, these results point to MUC1 and hTERT as the most promising targets for application in immunotherapeutic strategies for endometrial carcinoma and uterine sarcoma patients." (PMID 27618037, 2016). "In this study, we generated two novel human MUC1- expressing mouse models of oviductal and endometrial cancers respectively, based on simultaneous KrasG12D activation and Pten deletion mutations." (PMID 25078979, 2014). "In our study, mucinous subtype of endometrial carcinoma was studied; all small biopsies were excluded; the tumor origin was surgically verified by examining the gross specimen; new antibody (MUC1); and new monoclonal antibody clones for ER and PR were used." (PMID 16409624, 2006). "We used endometrial cancer lines isolated from well-, moderately- and poorly-differentiated tumors, suggesting that this may be a general characteristic of MUC1-expressing endometrial cancers." (PMID 27092881, 2016). "This study investigates the mechanism and functional consequences of MUC1 driven EGFR expression and signaling in endometrial cancer." (PMID 27092881, 2016). "This study shows that MUC1 increases EGFR mRNA and protein expression in endometrial cancer cells, extending observations as reported in other cell types." (PMID 27092881, 2016). "It is possible that MUC1 and EGFR targeted co-therapies may provide a new avenue for the treatment of advanced endometrial cancer." (PMID 27092881, 2016). "We show for the first time that MUC1 stimulates EGFR expression and function in endometrial cancer." (PMID 27092881, 2016). "Future evaluation of advanced endometrial cancer for MUC1 and EGFR expression followed by co-targeting may provide a new avenue for the treatment of advanced endometrial cancer." (PMID 27092881, 2016). "MUC1-directed therapies have not been tested in endometrial cancer, but there are promising results from MUC1 immunotherapy and ongoing MUC1 inhibitor clinical trials (NCT01279603, NCT02204085)." (PMID 27092881, 2016). "It would follow that co-targeting of MUC1 and EGFR in endometrial cancer could provide a more effective therapy than targeting EGFR alone." (PMID 27092881, 2016). "The combined influence of MUC1 and EGFR has not been studied in endometrial cancer and any physiological or clinical relevance of their co-regulation is not known." (PMID 27092881, 2016).
esophageal squamous cell carcinoma (9 papers, 2015 to 2024). Esophageal squamous cell carcinoma (ESCC) is a type of esophageal carcinoma (EC) that can affect any part of the esophagus, but is usually located in the upper or middle third. "In addition, MUC1 can also be used as a useful marker for predicting poor prognostic factors for 5-year survival outcome after radical esophageal squamous cell carcinoma resection." (PMID 33889544, 2021).
gastric tumor (9 papers, 2011 to 2025). "MUC1 is a glycoprotein that is highly overexpressed in most epithelial tumors, including gastric tumors." (PMID 41154387, 2025). "One of the main carriers of O-glycans in most tumors, including gastric tumors, is the transmembrane MUC1 mucin." (PMID 41154387, 2025). "Similarly, EpCAM, a widespread marker on epithelial carcinomas, and MUC1, a glycoprotein aberrantly glycosylated in gastric tumors, serve as attractive targets for next-generation CAR-T constructs." (PMID 41614808, 2025). "It has been shown that there are different patterns of protein expression between cardia and non-cardia carcinoma in terms of several markers, such as CD44, Mucin 1 (MUC1), and Cyclin-Dependent Kinase Inhibitor 2A (CDKN2A)." (PMID 35096085, 2022). "As with MUC1, TFF2 was significantly decreased in non-cardia and cardia tumor tissues compared with that in adjacent normal tissues (P = 4.00 × 10− 21 and P = 3.29 × 10− 14, respectively)." (PMID 32122390, 2020).
oral squamous cell carcinoma (9 papers, 2011 to 2025). "In oral squamous cell carcinoma (OSCC), silencing MUC1 can reduce the expression of Slug, thereby inhibiting tumor cell proliferation, inhibiting DNA replication, and inducing OSCC cell apoptosis." (PMID 33889544, 2021). "The efficacy of anti-MUC1 MAb C595 has been reported in oral squamous cell carcinomas (OSCCs), where MAb C595 induced complement-dependent cytotoxicity (CDC) and antibody-dependent cellular cytotoxicity (ADCC) to OSCC cells; this effect was strongly correlated with MUC1 expression." (PMID 21931707, 2011).
renal carcinoma (9 papers, 2014 to 2026). A carcinoma arising from the epithelium of the renal parenchyma or the renal pelvis. "In addition, MUC1 expression was associated with increased renal cancer cell proliferation and migration and had a prognostic role in patients affected by ccRCC." (PMID 36902242, 2023). "Overall, these findings suggested that MUC1 overexpression, through induction of the Warburg effect, increased the vulnerability of renal cancer cells to sunitinib treatment." (PMID 41533164, 2026). "Overall, these results demonstrate that MUC1 expression regulates the proliferation, migration, and invasion of renal cancer cells." (PMID 38254882, 2024). "Overall, these results show that the expression of MUC1 in renal cancer cells is a determinant of targeted therapy responses." (PMID 38254882, 2024). "To better define the role of MUC1 in additional renal-cancer-associated processes, we performed a GSEA using the Jones cohort (GSE15641) and stratified the patients according to MUC1 expression." (PMID 36902242, 2023). "In our pilot studies, we examined the expression of EpCAM, MUC1 and cytokeratins in renal carcinoma tissues." (PMID 35054482, 2022). "Herein, we demonstrated a nuclear localization of MUC1-C in renal cancer MUC1 expressing cells and 786-O scramble clones (data not shown)." (PMID 24504508, 2014). "Altogether, these results indicate that MUC1 (over)expression in renal cancer cells increases migration, invasion, cell viability, resistance to anoikis and decreases cell-cell interaction." (PMID 24504508, 2014). "In this study, to decipher the impact of MUC1 expression on renal cancer cell properties, MUC1 was either ectopically expressed in ACHN cells or knockdown in 786-O cells." (PMID 24504508, 2014). "The role of MUC1 in the migration properties of renal cancer cells was assessed using Boyden chambers and wound healing assays; we observed significant enhanced migration in ACHN clones expressing MUC1 by 8.3- and 2-fold, respectively." (PMID 24504508, 2014). "The purpose of this article was to better understand (a) the roles of MUC1 overexpression on renal cancer cells properties in vitro and in vivo and (b) the mechanism involved in MUC1-C nuclear localization." (PMID 24504508, 2014). "In conclusion, we report that MUC1 acts in renal cancer progression and MUC1-C nuclear localization drives invasiveness of cancer cells through a sheddase/gamma secretase dependent pathway." (PMID 24504508, 2014). "Altogether, these results show that MUC1 expression dramatically increases proliferative, migratory, invasive and anti-apoptotic signaling pathways in renal cancer cells." (PMID 24504508, 2014). "In addition, primary renal cancer cells treated with a small interfering RNA targeting MUC1 (siMUC1) migrated and proliferated at a slower rate than untreated cancer cells." (PMID 36430448, 2022). "In this context, we assessed the effects of MUC1 overexpression on renal cancer cells properties." (PMID 24504508, 2014). "However, the role of MUC1 in renal cancer remains unknown, especially in the context of metabolic reprogramming." (PMID 36430448, 2022). "In normal PTE cells, MUC1, ADAM10 and ADAM17 proteins were undetectable whereas all of them were expressed in RCC4, RCC10 and 786-O renal cancer cell lines." (PMID 24504508, 2014). "To assess MUC1 roles on kidney cancer cell properties, we used renal cancer cell lines expressing (786-O) or not (ACHN) MUC1 at protein levels." (PMID 24504508, 2014). "To assess whether MUC1 influences the tumoral properties of kidney cancer cells, we used renal cancer cell lines that either did (RCC4) or did not express (ACHN) MUC1." (PMID 38254882, 2024). "In addition, MUC1-silenced renal cancer cells proliferated at a slower rate than non-silenced cancer cells." (PMID 36430448, 2022). "In contrast, MUC1, ADAM10 and ADAM17 were absent in PTE cells while they were expressed in renal cancer cell lines." (PMID 24504508, 2014).
sarcoma (9 papers, 1998 to 2025). A usually aggressive malignant neoplasm of the soft tissue or bone. "The MUC-1 protein has been associated with sarcoma metastasis, and there is a current clinical trial using CAR-NK cells targeting MUC-1 in adult solid tumors (NCT02839954)." (PMID 37176035, 2023). "Although the majority of the positive sarcomas are attributable to these two types of tumors, we did find other sarcomatous tumors to be positive for MUC1." (PMID 27618037, 2016). "This is unexpected since MUC1 is an epithelial antigen and sarcomas are of mesenchymal origin." (PMID 27618037, 2016). "GD-2-specific CAR-T cells, as well as CAR-T cells specific to other sarcoma markers, CD133, HER2, Muc1 and CD117 are being tested in clinical trials (NCT03356782, NCT03356782, NCT04433221)." (PMID 37176035, 2023). "Freshly isolated primary sarcomas expressed activating ligands CD112 and low levels of CD155 and CD48 as well as the inhibitory ligands PCNA, MUC1, HLA-ABC, and HLA-DR/DP/DQ (n = 13)." (PMID 32082316, 2020).
urothelial carcinoma (9 papers, 2008 to 2025). A malignant neoplasm derived from the transitional epithelium of the urinary tract (urinary bladder, ureter, urethra, or renal pelvis). "MUC1 staining increased from normal urothelium (n = 27, 0.35±0.12) to urothelial carcinoma (UC, n = 323, H-score, 2.4±0.22, p≤0.0001)." (PMID 24671186, 2014). "Strong expression of MUC1 was also observed in urothelial carcinoma (UC)." (PMID 24671186, 2014). "Variation of MUC1 expression with grades of urothelial carcinoma." (PMID 24671186, 2014). "One study found that the positive rates of MUC1 and MUC2 in urothelial carcinoma were 89.7% and 44.3%, respectively, and MUC1 expression was significantly correlated with tumor grade, while MUC2 was the opposite." (PMID 35879749, 2022). "In this study, we explored the expression profile of transmembrane mucins (MUC1 and MUC4) in urothelial carcinoma tissue sections and three tissue TMAs." (PMID 24671186, 2014). "Expression of both MUC1 and MUC4, however, are significantly higher in urothelial carcinoma metastatic cases compared to localized UC." (PMID 24671186, 2014). "While aberrant changes were observed in expression and localization pattern of MUC1 between benign and malignant cases, significant downregulation of MUC4 was observed during urothelial carcinoma compared to normal and/or benign bladder tissues." (PMID 24671186, 2014). "MUC1-CAR-T cells exhibited selective cytotoxicity against MUC1-positive BC organoids, while combining decitabine with EGFR- or CD44v6-CAR-T cells enhanced cytotoxicity against urothelial carcinoma cell lines." (PMID 41425090, 2025). "In urothelial carcinoma cases, MUC1 staining varied from no reactivity (N = 38 or 12%), focal reactivity (N = 12 or 4%, mean H-score 0.057±0.01) to moderate (N = 147 or 46%, mean H-score 1.02±0.05) and intense immunoreactivity (N = 117 or 37%, mean H-score of 2.86±0.02)." (PMID 24671186, 2014).
invasive breast carcinoma (8 papers, 2006 to 2022). A carcinoma that infiltrates the breast parenchyma. "MUC1 overexpression has been associated with shorter BCSS in invasive breast cancer but in cases primarily receiving surgical treatment and not specific to older women." (PMID 33226492, 2021). "To validate the relationship of GATA3 and MUC1 in breast tissues further, we performed mRNA expression analyses of 36 invasive breast carcinomas by real-time RT-PCR, and protein expression analysis in 263 breast tissue samples by means of immunohistochemistry on TMAs." (PMID 17078870, 2006).
ulcerative colitis (8 papers, 2017 to 2024). An inflammatory bowel disease involving the mucosal surface of the large intestine and rectum. "MUC1 is one of the most studied membrane-associated mucins and is upregulated in the inflamed intestine and in ulcerative colitis in humans." (PMID 33319326, 2021). "Altered glycosylation of the oncoprotein MUC1 commonly occurs in chronic inflammation, including ulcerative colitis, and this aberrantly glycosylated MUC1 promotes cancer development and progression." (PMID 38699634, 2024). "Animals with ulcerative colitis have reduced levels of MUC-1 (95%, p < 0.0001) when compared to the control group (95804 ± 12615 pixels/field)." (PMID 36285298, 2022). "In support of the importance of MUC1 in protection, patients with ulcerative colitis had increased expression of Muc1 in inflamed tissue." (PMID 33502317, 2021). "However, MUC1 has been found to be upregulated in the inflamed intestines of mice infected with enteric pathogens as well as in human patients with ulcerative colitis." (PMID 28588132, 2017). "For example, MUC1 overexpression generated anti-MUC1 antibodies that could damage colon cells through cell-dependent cytotoxicity, leading to chronic intestinal inflammation such as ulcerative colitis (UC)." (PMID 39234554, 2024).
acute lung injury (7 papers, 2011 to 2022). A condition of lung damage that is characterized by bilateral pulmonary infiltrates (pulmonary edema) rich in neutrophils, and in the absence of clinical heart failure. "A previous study examined KL-6/MUC1 levels in the serum and pulmonary epithelial lining fluid (ELF) or bronchoalveolar lavage fluid (BALF) of patients with ARDS or acute lung injury (ALI)." (PMID 33672761, 2021).
clear cell renal cell carcinoma (7 papers, 2009 to 2026). "Mucin1 (MUC1), a glycoprotein associated with an aggressive cancer phenotype and chemoresistance, is aberrantly overexpressed in a subset of clear cell renal cell carcinoma (ccRCC)." (PMID 36902242, 2023). "In clear-cell renal cell carcinoma models, stabilization of HIF-1α by CoCl2 led to increased MUC1 mRNA levels, whereas HIF-1α knockdown via small interfering RNA and the HIF-1 inhibitor YC-1 reduced hypoxia-induced MUC1 expression." (PMID 41416421, 2026).
diabetes (7 papers, 2020 to 2024). "One of the causes of fertility problems in diabetes, is changes in Muc1 expression during implantation.On the other hand, the use of insulin in these patients can even lead to overexpression of this gene and worsen thecondition." (PMID 33098389, 2020). "Therefore, this study aimed to investigate the impacts of diabetes andinsulin, metformin and pioglitazone on Muc1 expression at the time of implantation." (PMID 33098389, 2020). "Therefore, thisstudy aimed to investigate the impacts insulin, metformin and pioglitazone as well assuperovulation on the expression profile of Muc1 during the implantationprocess, by using experimental rat diabetes model (type 1 and type 2 diabetes)." (PMID 33098389, 2020). "Mucin-1(Muc1) is one of the first molecules in the endometrium that confronts implanting embryos.There is insufficient knowledge about the impacts of diabetes and drugs developed for diabetes treatment on expres-sion of this molecule at the time of implantation." (PMID 33098389, 2020). "Although the same lead SNP (rs11264341) in MUC1/TRIM46 did not provide evidence of a causal relationship between serum uric acid and incident diabetes, in people without a history of diabetes." (PMID 38279093, 2024).
inflammatory bowel disease (7 papers, 2008 to 2023). A spectrum of small and large bowel inflammatory diseases of unknown etiology. "REG1B protein is highly expressed in several human pathologies, such as inflammatory bowel disease, many of which are associated with epithelial inflammation, indicating that the gastric mucosa of Muc1−/− mice is more inflamed than WT mice within 8 h of infection." (PMID 32793510, 2020). "In fact the MUC1 gene has been linked with susceptibility to inflammatory bowel disease." (PMID 27242727, 2016). "It has been suggested that down-regulation of mucin 1 (MUC1) in hematopoietic cells increases MDSCs expansion in inflammatory bowel disease (IBD) leading to the development of CRC." (PMID 33384962, 2020). "MUC1 expression in biopsies from inflammatory bowel disease patients with chronic inflammation was also higher during acute infection compared to the inflammatory bowel disease control biopsies." (PMID 19088856, 2008). "A previous study, which used interleukin 10-deficient mice crossed with MUC1.Tg mice that developed spontaneous inflammatory bowel disease, showed that vaccination with a Tn-MUC1 100-mer peptide could reduce inflammation." (PMID 36980805, 2023).
lung injury (7 papers, 2008 to 2023). "In the setting of experimental acute kidney injury, a protective role of MUC1 has been identified in the early phase of the insult in mouse models of ischemia reperfusion injury." (PMID 37316299, 2023). "Concurrently, the negative regulatory effect of MUC1 on the TLR4/MyD88/NF-κB pathway has been described in other diseases, such as acute lung injury and acute kidney injury." (PMID 37880668, 2023).
osteosarcoma (7 papers, 2007 to 2024). A usually aggressive malignant bone-forming mesenchymal neoplasm, predominantly affecting adolescents and young adults. "High expression of MUC1 is correlated with low survival of osteosarcoma patients, which is consistent with our results that MUC1 acts as a risk factor in our signature." (PMID 36899330, 2023). "Transcriptome analysis showed that a high expression of GALNT14 and MUC1 in osteosarcoma was associated with poor prognosis." (PMID 36405691, 2022). "As a survival-related upregulated gene in osteosarcoma, MUC1 was selected as a potential independent prognostic candidate gene, and has been associated with metastatic progression both in vivo and in vitro in several cancer types." (PMID 36899330, 2023). "Five ferroptosis-associated genes (MUC1, MAP3K5, LURAP1L, HMOX1, and BNIP3) correlated with the prognosis of osteosarcoma were screened for the construction of the risk score model." (PMID 36899330, 2023). "qRT-PCR showed that the expression of GALNT14 in osteosarcoma cell lines was also higher than that in the osteoblast cell line, while the opposite result can be seen in MUC1." (PMID 36405691, 2022). "However, the results of qRT-PCR showed that the expression of MUC1 in osteosarcoma cell lines was lower than that in osteoblastic cell lines, which may be related to hypermethylation or co-expression inhibition of other genes." (PMID 36405691, 2022). "Similarly, several survival-related genes, including MUC1, COL13A1, KAZALD1, and JAG2, were identified as prognostic markers in osteosarcoma by scRNA-seq and TARGET analysis." (PMID 39324133, 2024). "Six of these genes are increased (MYOM2, VEGFA, MUC1, IHH, GLI1 and GRIA1) and seven are decreased (VCAM1, EGFR, GPC3, IGF2, GNG12, GNGT1 and C3) in localized patients with poor prognosis that either relapse or die due to osteosarcoma." (PMID 38538763, 2024).